PRSS56 (serine protease 56)
Description:
Serine protease required during eye development.
Synonyms: MCOP6
Tractability: Antibody: UniProt predicts a signal peptide or a membrane-spanning region.
Gene: Protein-coding gene on chromosome 2 (232,520,388 to 232,525,716, forward strand). Ensembl gene ENSG00000237412.
Gene Ontology:
Molecular function: serine-type endopeptidase activity
Biological process: camera-type eye development; blood coagulation; proteolysis
Cellular component: endoplasmic reticulum
Genetic constraint (gnomAD): Loss-of-function variants: 52 observed, 59.01 expected, observed/expected ratio (o/e) 0.88, 90% interval 0.7 to 1.11. The upper end of that interval is the gene's LOEUF score, 1.11, which puts it in group 4 of 6, group 1 being the genes least tolerant of losing a copy. Missense variants: 864 observed, 775.21 expected, observed/expected ratio (o/e) 1.11, 90% interval 1.05 to 1.18. Synonymous variants: 408 observed, 356.61 expected, observed/expected ratio (o/e) 1.14, 90% interval 1.05 to 1.24.
Gene-disease validity (ClinGen):
ClinGen rates the evidence that PRSS56 causes each of these diseases.
isolated microphthalmia 6 (autosomal recessive): Definitive.
Homologues: Orthologues: chimpanzee PRSS56 (98% identical), macaque PRSS56 (97% identical), dog PRSS56 (86% identical), pig PRSS56 (85% identical), mouse Prss56 (79% identical), guinea pig PRSS56 (74% identical), rat Prss56 (71% identical), rabbit PRSS56 (69% identical), tropical clawed frog PRSS56 (39% identical), zebrafish prss56 (16% identical), Drosophila melanogaster CG33458 (13% identical), Drosophila melanogaster CG33459 (12% identical), and 1 more. Paralogues in human: LPA (16% identical).
Diseases named in the same sentence as PRSS56 in open-access papers:
PRSS56 is named in the same sentence as 29 diseases in open-access papers, as found by Europe PMC text mining. Sharing a sentence is not in itself a finding about the gene and the disease. The quoted sentences say what the papers report.
nanophthalmos (15 papers, 2011 to 2025). "We conclude that, in mice, Mfrp, Prss56, and Adipor1 mutations yield similar microphthalmia phenotypes involving both the anterior and posterior eye." (PMID 40154727, 2025). "Mutations in PRSS56 cause nanophthalmos or autosomal-recessive posterior microphthalmos; mutations in FBN1 have been linked to Marfan syndrome (MFS) and Weill–Marchesani syndrome, both of which are characterized by high myopia and ectopia lentis." (PMID 35285860, 2022). "We have previously reported that a mutation in PRSS56 causes nanophthalmos, a condition characterized by severe ocular axial length reduction." (PMID 32152063, 2020). "PRSS56 is another human gene in which mutations can cause recessive nanophthalmos and variants of this gene are also associated with myopia." (PMID 32236127, 2020). "The availability of Prss56 mutant mice exhibiting reduced ocular axial length and recapitulating hallmark features of human nanophthalmos constitutes a unique resource to mechanistically dissect the molecular pathways contributing to ocular size determination." (PMID 29529029, 2018). "PRSS56 mutations are a major cause of nanophthalmos, characterized by severe shortening of ocular axial length and high hyperopia, and polymorphisms at PRSS56 have been previously reported to be associated with RE and myopia, angle-closure glaucoma, and ocular abnormalities in humans and mice." (PMID 37351342, 2023). "Using two distinct mouse models of nanophthalmos and a combination of genetic approaches, we identified a retinal gene expression signature characterized by the upregulation of the genes coding for PRSS56 and ADAMTS19 that is associated with the reduced ocular size." (PMID 33755662, 2021). "Interestingly, elevated levels of retinal Prss56 expression have recently been reported in another mouse model of nanophthalmos caused by a mutation in the gene coding for membrane frizzed related-protein (Mfrp)." (PMID 33755662, 2021). "Besides Prss56, Tmem98 was the only other differentially expressed gene that has previously been implicated in nanophthalmos and was found to be significantly downregulated in the retina from Prss56-/- mice compared to control Prss56+/- mice." (PMID 33755662, 2021). "Furthermore, we and other groups have shown that PRSS56 mutations lead to nanophthalmos (posterior microphthalmia) and extreme hyperopia characterized by significant reduction in ocular axial length in humans." (PMID 29529029, 2018). "Interestingly, PRSS56/Prss56 mutations are associated with autosomal recessive posterior microphthalmia in humans and mice." (PMID 25357075, 2014). "Three of the candidate genes discovered in our GWAS for eye size – PRSS56, ADAMTS19, and PIEZO2 – are of particular interest by virtue of their known or suggested role in causing nanophthalmos or microphthalmos." (PMID 34698770, 2021). "Consistent with this, Prss56 and Mfrp mutant mice recapitulate the cardinal features of nanophthalmos, i.e. reduced ocular axial length and hyperopia." (PMID 33755662, 2021). "Mutations in human PRSS56 and MFRP are responsible for nanophthalmos that exhibit a severe reduction in ocular axial length, and high hyperopia." (PMID 33755662, 2021). "Mutations in PRSS56 and MFRP constitute a major cause of nanophthalmos, a condition characterized by severe reduction in ocular axial length/extreme hyperopia." (PMID 33755662, 2021). "To date, six genes (PRSS56, MFRP, TMEM98, CRB1, BEST1, and MYRF) have been implicated in familial forms of nanophthalmos, with PRSS56 and MFRP mutations being the most prevalent among multiple cohorts." (PMID 33755662, 2021). "While six genes have been implicated in this hereditary condition (MFRP, PRSS56, MYRF, TMEM98, CRB1,VMD2/BEST1), the relative contribution of these to nanophthalmos or to less severe high hyperopia (≥ + 5.50 spherical equivalent) has not been fully elucidated." (PMID 33203948, 2020).
nanophthalmos (continued). "For example, in Chinese populations, variants in two of the most commonly mutated genes in isolated recessive nanophthalmos, MFRP and PRSS56, account for less than 6% and 8% of cases, respectively." (PMID 31048900, 2019). "To date, five genes (i.e., MFRP, TMEM98, PRSS56, BEST1, and CRB1) and two loci have been implicated in familial forms of nanophthalmos." (PMID 29862063, 2018). "Genes such as PRSS56 (and MFRP), for which loss of function causes nanophthalmos, have been considered potential targets for slowing the progression of myopia, because reducing their functional activity may prevent further ocular elongation." (PMID 34698770, 2021). "The mechanism by which sequence changes in PRSS56 cause nanophthalmos has not been fully explained; it has been suggested the encoded protein is part of a complex regulatory network influencing postnatal eye development." (PMID 32454992, 2020). "We, and others, have previously demonstrated that mutations in the gene coding for the secreted serine protease PRSS56 result in a reduction in ocular axial length (nanophthalmos) in humans, and many of these individuals go on to develop angle-closure glaucoma (ACG)." (PMID 32152063, 2020). "Thus far, genes identified in Mendelian cases of nanophthalmos have different roles in the retina (PRSS56, CRB1) and the retinal pigment epithelium (BEST1/VMD2, MFRP)." (PMID 31048900, 2019). "Consistent with ocular findings in Prss56-/- mice, the human PRSS56 mutation led to a substantial reduction in VCD compared to a normal emmetropic eye, suggesting that PRSS56 mutations leading to nanophthalmos and extreme hyperopia in humans likely act via a loss of function mechanism." (PMID 29529029, 2018).
myopia (10 papers, 2013 to 2026). "Given the role of PRSS56 in supporting ocular growth at stages following opening of the eyelid, targeting PRSS56 appears a viable therapeutic strategy to slowdown axial elongation underlying myopia." (PMID 29529029, 2018). "We have previously identified a role for the secreted serine protease PRSS56 in ocular size determination and PRSS56 variants have been implicated in the etiology of both hyperopia and myopia, highlighting its importance in refractive development." (PMID 29529029, 2018). "Since the loss of PRSS56 function leads to reduced ocular size, PRSS56 variants associated with myopia (identified by GWAS) likely act in an opposite manner, i.e. via a gain of function mechanism, to induce ocular axial elongation." (PMID 29529029, 2018). "Since PRSS56 variants have been implicated in both human hyperopia and myopia, our findings have direct relevance to human ocular refractive development." (PMID 29529029, 2018). "The implication of PRSS56 variants in both hyperopia and myopia suggests a critical role for PRSS56 in ocular axial growth regulation and refractive development." (PMID 29529029, 2018). "Most interestingly, an increased temporal expression of Prss56, a gene linked to posterior microphthalmia and associated with ocular growth defects in myopia was observed." (PMID 25357075, 2014). "Transcripts of Prss56, a gene associated with angle-closure glaucoma, posterior microphthalmia and myopia, were increased in Mfrprd6 eyes by 17-fold." (PMID 25357075, 2014). "Using a complementary genetic approach, we show that loss of PRSS56 or MFRP function prevents excessive ocular axial growth in a mouse model of early-onset myopia caused by a null mutation in Irbp, thus, demonstrating that PRSS56 and MFRP are also required for pathological ocular elongation." (PMID 33755662, 2021). "Moreover, we demonstrate that loss of PRSS56 or MFRP function prevents excessive ocular axial elongation in a mouse model of early-onset myopia caused by a null mutation in Irbp, further establishing PRSS56 and MFRP as critical regulators of ocular growth." (PMID 33755662, 2021). "To explore the translational potential of this finding, we tested the hypothesis that inactivation of PRSS56-mediated pathway(s) could slowdown axial elongation linked to myopia." (PMID 29529029, 2018). "Importantly, we demonstrate that genetic inactivation of Prss56 can rescue axial elongation in a mouse model of myopia caused by loss of EGR1 function." (PMID 29529029, 2018). "Collectively, our findings suggest that therapeutic strategies targeting PRSS56 to modulate ocular growth could have important clinical implications to prevent or slowdown the progression of myopia and associated blinding conditions in humans." (PMID 29529029, 2018). "Moreover, two different genome-wide association studies (GWAS) involving multi-ethnic cohorts identified Prss56 as significantly associated with refractive errors and myopia that relate to a change in axial length." (PMID 25357075, 2014). "Interestingly, retinal Prss56 expression levels are upregulated in response to lens-induced hyperopic defocus that caused ocular axial elongation/myopia in marmosets suggesting a potential of Prss56 in emmetropization, which is avision-guided process ocular growth." (PMID 37351342, 2023). "Guinea pig myopia models consistently exhibited high Prss56 expression, and short-wave light exposure reduced Prss56 mRNA levels and attenuated further axial elongation." (PMID 41917313, 2026). "Consistent with this notion, a recent study has shown that optical defocus-induced axial elongation/myopia in marmoset is accompanied by increased expression of Prss56." (PMID 33755662, 2021). "Consistent with our ocular size findings, refraction was significantly rescued in double mutants compared to single Egr1 or Prss56 mutants, exhibiting myopia or hyperopia, respectively." (PMID 29529029, 2018).
myopia (continued). "Compared with matched controls, increased PRSS56 expression was observed in both patient-derived iPSCs carrying c.-187G>T and knock-in mice (c.-155G>T, corresponding to human c.-187G>T) that faithfully recapitulate myopia phenotypes." (PMID 41917313, 2026). "Using a complementary genetic approach, we show that besides promoting ocular growth during normal development, PRSS56 and MFRP are also required for pathological ocular elongation observed in a mouse model of severe and early-onset myopia caused by a null mutation in Irbp." (PMID 33755662, 2021). "Finally, we demonstrate that Prss56 inactivation rescues axial elongation in a mouse model of myopia." (PMID 29529029, 2018). "Overall, these results demonstrate that Prss56 inactivation rescues axial elongation/myopia resulting from EGR1 deficiency, and thereby establish PRSS56 as a potential therapeutic target for interventions aimed at preventing myopia." (PMID 29529029, 2018). "Importantly, we have uncovered a previously unrecognized role for retinal Müller glia in ocular growth and demonstrated that Prss56 inactivation has translational potential to rescue axial length elongation in a mouse model of myopia." (PMID 29529029, 2018).
hyperopia (6 papers, 2018 to 2025). A refractive error in which rays of light entering the eye parallel to the optic axis are brought to a focus behind the retina, as a result of the eyeball being too short from front to back. "Consistent with human genetic studies, we have demonstrated previously that loss of PRSS56 function in the mouse leads to ocular axial length reduction and hyperopia." (PMID 33755662, 2021). "In summary, we demonstrate that loss of PRSS56 function leads to ocular size reduction and hyperopia and identify a novel role for Müller glia in ocular axial growth." (PMID 29529029, 2018). "Here, we use a combination of genetic mouse models to demonstrate that Prss56 mutations leading to reduced ocular size and hyperopia act via a loss of function mechanism." (PMID 29529029, 2018). "Using mice homozygous for a null allele of Prss56, we demonstrate that loss of PRSS56 function causes a reduction in ocular size and hyperopia, suggesting that impaired processing of PRSS56 protease’s endogenous substrate(s) may underlie ocular size reduction." (PMID 29529029, 2018). "We show that loss of PRSS56 function causes ocular axial length reduction and hyperopia." (PMID 29529029, 2018). "Several genes (e.g., BEST1, CRB1, MFRP, PRSS56 and TMEM98) which have roles in both foetal ocular development and post-natal outer retinal maintenance, can be associated with high hyperopia and short axial length." (PMID 41465105, 2025). "Together these findings show that Prss56-/- mice have reduced ocular size, develop hyperopia, and recapitulate the ocular phenotypes observed in the previously characterized ENU-induced Prss56glcr4 mutant mice, demonstrating that loss of PRSS56 function leads to reduced ocular size." (PMID 29529029, 2018).
autosomal recessive nanophthalmos (2 papers, 2020 to 2022). "Herein, we expand the spectrum of PRSS56 variants causing autosomal recessive nanophthalmos and describe the associated phenotype in two individuals from a consanguineous Czech Roma family." (PMID 32454992, 2020). "Nanophthalmos type 2 (NNO2; #609549) and isolated microphthalmia type 6 (MCOP6; OMIM #613517) are autosomal recessive conditions associated with pathogenic variants in the membrane frizzled-related protein (MFRP) and serine protease 56 (PRSS56) genes, respectively." (PMID 32454992, 2020).
colon cancer (2 papers, 2023 to 2025). "Particularly, the frequency of PRSS56 overexpression in gastrointestinal cancer was 8.8% in esophagus cancer, 11.6% in gastric cancer, 32.1% in colon cancer, 44.1% in rectal cancer, and 15.1% in liver cancer, respectively." (PMID 37400936, 2023). "The transcriptome, metabolome, and combined omics analysis showed that the changes in colon cancer organoids after inhibition of PHGDH were mainly involved in PRSS1 and PRSS56, steroid hormone biosynthesis, phenylalanine metabolism, ascorbate and aldarate metabolism, and tyrosine metabolism." (PMID 39670663, 2025).
colorectal cancer (2 papers, 2023 to 2026). A primary or metastatic malignant neoplasm that affects the colon or rectum. "Additionally, Dandan Li’s research indicated that the PRSS56 gene promotes colorectal cancer progression via the PI3K/AKT signaling axis." (PMID 41595533, 2026). "In this study, we first confirmed the oncogenic roles of PRSS56 in gastric and colorectal cancer." (PMID 37400936, 2023). "In our study, TCGA analysis revealed that genes such as those from the SPRR family, MUC6, KRT family, SLC26A9, MMP7, PRSS56, and SFRP1 were highly expressed in the colorectal cancer group." (PMID 41595533, 2026). "A heatmap of the top 50 differentially expressed genes was generated, highlighting that genes such as SPRR family members, MUC6, KRT family genes, SLC26A9, MMP7, PRSS56, and SFRP1 were highly expressed in the colorectal cancer group." (PMID 41595533, 2026). "Our RNA-Seq analysis also found that 5’-Aza-CdR exposure resulted in overexpression of multiple CT antigens in gastric cancer and colorectal cancer, including SSX1, TKTL1, SPANXB1, PNMA5, PNMA6E, GAGE12J, and PRSS56." (PMID 37400936, 2023). "Given PRSS56 was greatly overexpressed in GC and CRC, we herein selected a gastric cancer cell line AGS and a colorectal cancer cell line HCT116 for DNA methyltransferase inhibitor treatment." (PMID 37400936, 2023). "On the contrary, the testis-specific serine proteases, such as PRSS56 and PRSS41, were greatly reactivated in stomach cancer and colorectal cancer." (PMID 37400936, 2023).
gastric cancer (2 papers, 2023 to 2025). A primary or metastatic malignant neoplasm involving the stomach. "PRSS56 expression was significantly activated in colorectal and gastric cancer cells exposed to DNA methyltransferase inhibitors." (PMID 37400936, 2023). "Notably, PRSS56 was the most significantly up-regulated testis-specific serine protease in gastric cancer." (PMID 37400936, 2023). "In addition, the GO/KEGG analysis has confirmed that PRSS56 overexpression exhibits high immunogenicity and was positively associated with PI3K/AKT axis in gastric cancer patients." (PMID 37400936, 2023).
retinal degeneration (2 papers, 2014 to 2025). Degeneration of the retina. "Micropthalmia was observed independent of retinal degeneration (Mfrprd6, Adipor1tm1Dgen) or retinal thickening (Prss56 mutants)." (PMID 40154727, 2025). "Increased expression was observed during postnatal eye development in Müller cells of Mfrprd6 mutants, but not in other similarly affected retinal degeneration models, suggesting that Prss56 upregulation is unique to Mfrp disruption." (PMID 25357075, 2014).
bile duct cancer (1 paper, 2022). "PRSS56 encodes a serine protease, which has a significant correlation with clinical stage in bile duct cancer." (PMID 36293321, 2022).
brain cancer (1 paper, 2023). A primary or metastatic malignant neoplasm affecting the brain. "The CT antigen PRSS56 was selectively expressed in early spermatids of normal testis and widely upregulated in various cancers other than testis and brain cancer, especially in gastrointestinal cancer." (PMID 37400936, 2023).
glaucoma (1 paper, 2020). Increased pressure in the eyeball due to obstruction of the outflow of aqueous humor. "Overall, our data suggest that PRSS56 is a critical component of a developmental program regulating iridocorneal angle configuration and that alterations in this process may constitute a risk factor for high IOP and glaucoma." (PMID 32152063, 2020). "Collectively, our findings point to a role for PRSS56 in the development and maintenance of ocular drainage tissues and IOP homeostasis, and provide new insights into glaucoma pathogenesis." (PMID 32152063, 2020).
Kyphoscoliosis (1 paper, 2025). An abnormal curvature of the spine in both a coronal (lateral) and sagittal (back-to-front) plane. "We identified 11.62% (5/43) and 12.82% (5/39) of Prss56-Nf1fl/fl, 14.28% (3/21), and 17.25% (5/29) of Prss56-Nf1fl/- mutant mice manifesting kyphoscoliosis at 12 and 14-20 months of age, respectively." (PMID 41397954, 2025). "Analyses performed on Prss56-Nf1 mutant mice revealed progressive scoliosis, kyphosis, and kyphoscoliosis, closely mirroring the spine deformities observed in patients with NF1." (PMID 41397954, 2025).